GAST (gastrin)
Diseases named in the same sentence as GAST in open-access papers (continued):
Sharing a sentence is not in itself a finding about the gene and the disease.
Obesity (17 papers, 2011 to 2025). Accumulation of substantial excess body fat. "Obesity is associated with a range of changes in metabolic cytokines and hormones, including leptin, gastrin, insulin, and certain central lipids." (PMID 40150457, 2025). "Further investigation is needed in order to determine if the HbA1c correlated responsiveness to exogenous gastrin is linked to this increase in CCK production within the islets during obesity which is known to correlate with increased HbA1c1." (PMID 31430329, 2019). "Oral administration of Gastrin‐SiO2 microspheres in these mice improved blood glucose control and decreased insulin resistance and obesity (the main hallmarks of T2D) in the HFD‐fed C57BL/6J mice." (PMID 39950948, 2025). "Mice specifically lacking MafA in β cells demonstrated broad, population-wide changes in hormone gene expression with an overall gene signature closely resembling islet gastrin+ (Gast+) cells generated under conditions of chronic hyperglycemia and obesity." (PMID 37606041, 2023). "Basal concentrations and responses to an oral glucose tolerance test of glucagon, GLP-1, GIP, CCK, and gastrin at baseline and after matched ~6% weight loss by a CD or a CRHP diet in individuals with T2D and overweight or obesity." (PMID 36061897, 2022). "Ghrelin levels are known to be decreased in obesity, while the density of somatostatin-producing cells remains unchanged in the gastric mucosa of obese mice, and plasma gastrin levels are increased in HFD mice." (PMID 32824949, 2020). "The current working model hypothesizes that gastric myoelectrical activity might be associated with the main gastric hormones, such as ghrelin, irisin, and gastrin, in different obesity phenotypes." (PMID 35547577, 2022). "Three clusters were enriched for behavioural phenotypes (Cluster053, Cluster027 and Cluster042), two clusters showed vascular and respiratory phenotypes (Cluster048 and Cluster045) and two small clusters contained genes related to gastrin release and obesity (Cluster089 and Cluster096)." (PMID 28190221, 2017). "QTL for NVD was homologous with HSA 17q21 regions which contained many obesity candidate genes including PPY, PON1 and 2, GAST, PNMT, STAT3 and HCRT." (PMID 23977060, 2013). "The pancreatic beta cell mass is dynamic and can increase when exposed to appropriate environmental and physiological changes, such as obesity and pregnancy, and growth stimuli such as BTC, glucagon-like peptide-1 and gastrin." (PMID 21897861, 2011). "However, studies are required to elucidate the effect of increased PC1/3 on gastrin and ghrelin secretion in HFD-induced obesity." (PMID 32824949, 2020). "GRP is a regulatory neuropeptide that stimulates gastric G cells to release gastrin and regulate gastric acid secretion and intestinal movement, which affects the food intake and may lead to anorexia, bulimia, and obesity if lacked of the genes." (PMID 31024621, 2019).
dyspepsia (16 papers, 2010 to 2026). An uncomfortable, often painful feeling in the stomach, resulting from impaired digestion. "In particular, considering the Hp-associated dyspepsia, gastrin levels increase during Hp infection and return to normal after eradication of the infection." (PMID 23762836, 2013). "Through our research, we suggest that Sorafenib may cause dyspepsia by inhibiting p38, thereby inducing gastrin, which may result in dyspepsia." (PMID 30791472, 2019). "Effect of different doses of hesperidin on serum motilin (MTL) and gastrin (GAS) contents in functional dyspepsia rats." (PMID 36034863, 2022). "Dyspepsia mice showed dyspepsia reactions and proximal gastric relaxation reduction, characterized by a significant decrease of contents of gastrin (P < 0.01) and cholinesterase (P < 0.01)." (PMID 33029172, 2020). "Through our research, we suggest p38 and gastrin as entities that can connect Sorafenib to its known side effect, dyspepsia." (PMID 30791472, 2019). "Dyspepsia is highly related to gastrin, as gastrin is a key regulator for the secretion of gastric acid, a digestive fluid formed in the stomach." (PMID 30791472, 2019). "Moreover, CagA-positive H. pylori strains have been shown to affect the secretion of several hormones, including 5-HT, ghrelin, dopamine, and gastrin, and altered levels of these hormones might be the cause of the psychological disorders of functional dyspepsia patients." (PMID 27840636, 2016). "Studies have shown that Aurantii fructus can increase the secretion of motilin, gastrin, and vasoactive peptide substances, relieve gastrointestinal motility disorders, regulate intestinal flora in rats with dyspepsia, promote the growth of beneficial bacteria, and thus treat FD." (PMID 38495103, 2024). "For example p38 and gastrin are related entities that connect Sorafenib to dyspepsia." (PMID 30791472, 2019). "The present findings of increased gastrin and decreased somatostatin in all IBS subtypes may cause a high level of gastric acid secretion, which may account for the high incidence of dyspepsia and gastro-oesophageal reflux observed in patients with IBS." (PMID 25110039, 2014). "Hp positive asymptomatic subjects showed higher gastrin level than Hp negative ones, suggesting that hypergastrinemia in the early phase of Hp infection predisposes or contributes to Hp-related dyspepsia." (PMID 23762836, 2013). "This case presents a 69-year-old female who presented with dyspepsia, and on subsequent endoscopic evaluation, she was found to have AMAG in the context of elevated levels of serum chromogranin A (CgA) and gastrin, suggestive of a GNET." (PMID 41728546, 2026). "The increase in gastrin cell density and the decrease in somatostatin cell density in all IBS subtypes may cause high levels of gastric secretion, which may in turn contribute to the high incidence of dyspepsia and gastro-oesophageal reflux observed in patients with IBS." (PMID 25110039, 2014). "The so-called “GastroPanel” including pepsinogen I and II and gastrin 17 did not report that gastrin (using the old normal value) was useful, but the ratio of pepsinogen I to pepsinogen II was reduced in a group of patients with dyspepsia." (PMID 37941554, 2023).
carcinoids (15 papers, 1988 to 2025). "Histopathologically, gastrin is thought to cause carcinoids through a sequence of hyperplasia- dysplasia- neoplasia of the ECL cell." (PMID 25698559, 2015). "We evaluated the patient for carcinoid tumor small bowel recurrence by screening for gastrin, vasoactive intestinal peptide, and 24 h urine 5-hydroxytryptamine levels; all of these were within normal limits." (PMID 40126291, 2025). "While pathological gastrin levels are intricately linked to hyperplasia of enterochromaffin-like cells leading to carcinoid development, the signaling effects exerted by gastrin on distinct cell types of the gastric mucosa are more nuanced." (PMID 35330921, 2022). "The resulting Type II carcinoids develop in response to gastrin stimulating proliferation of the ECL cells." (PMID 35330921, 2022). "Multiple studies have shown the hyperplastic effects of gastrin on the gastric mucosa in the setting of antacid medication in rats, but the evidence for dysplasia or carcinoid development in humans is yet to be ascertained." (PMID 25698559, 2015). "It has been suggested that gastric carcinoids develop following progressive changes caused by gastrin stimulation, such as increasing hyperplasia of ECL-cells to dysplasia and carcinoid formation." (PMID 25698559, 2015). "The peptide most frequently detected in typical carcinoids was bombesin (67%), while gastrin was more common in neuroendocrine carcinomas (44%)." (PMID 2906252, 1988). "However, her levels of gastrin, vasoactive intestinal peptide, and 5-hydroxytryptamine from 24 h urine assessing for recurrent carcinoid were all within normal limits." (PMID 40126291, 2025). "The favored hypothesis entails ECL cell development into carcinoids due to chronic stimulation by high gastrin levels." (PMID 39669826, 2024). "This may indicate that the oncogenic potential of gastrin in carcinoid cells is at least as high as that of HGF." (PMID 15846300, 2005). "Carcinoid tumors secrete a variety of agents,including kallikrein, histamine, prostaglandins, adrenocorticotropic hormone,gastrin, calcitonin, and growth hormone; however, serotonin has received the mostattention in hypotheses concerning the genesis of heart disease." (PMID 27982350, 2016). "Although serum gastrin levels in the continuous maintenance therapy remained elevated, no adverse events such as carcinoid tumors were reported." (PMID 40777627, 2025). "The extent to which carcinoid tumors are regulated by other hormones is not clear; however, they do express receptors for IGF-1, somatostatin, and gastrin overproduction was linked to the development of at least a subtype of carcinoid tumors." (PMID 26290759, 2015). "In response to chronically elevated gastrin levels, ECL cell hyperplasia is induced and carcinoids may develop through the hyperplasia–dysplasia–neoplasia sequence." (PMID 25698559, 2015). "The presence of a number of regulatory peptides (bombesin, gastrin, glucagon, somatostatin, calcitonin and ACTH) was compared in 30 typical carcinoid tumours and 27 well differentiated neuroendocrine carcinomas (atypical carcinoids) using conventional immunocytochemistry." (PMID 2906252, 1988).
gastric tumor (15 papers, 1989 to 2025). "All conditions with reduced gastric acidity result in an increased risk of gastric tumours due to elevated gastrin in order to restore gastric acidity." (PMID 33266504, 2020). "In this study, we document a diminished expression of miR-449 in Gastrin KO mice and further confirmed its loss in human gastric tumours." (PMID 21418558, 2011). "One of the EBV lytic proteins, BMRF1, was previously shown to upregulate gastrin, and high levels of gastrin are implicated in gastric tumor development." (PMID 21194482, 2010). "Overall, these data demonstrated a novel mechanism that contributes to gastrin-induced gastric tumor development." (PMID 33066578, 2020). "H. felis was given to INSp-GAS (expression of gastrin under insulin promoter) transgenic mice, after which gastric tumor tissue was confirmed by histology after dissection out the formed tumor." (PMID 30844765, 2019). "The gastrin system plays an important role in the elevated morphology of gastric tumors." (PMID 32210918, 2020). "Treatment of anti-gastrin-17 antiserum significantly reduces proliferation of gastric tumor cells." (PMID 32210918, 2020). "Gastrin contributes to gastric tumor development via several cellular mechanisms." (PMID 27323780, 2016). "Increased gastrin-induced miR-222 expression leads to increased migration and the extension of long processes in AGSGR cells, cellular events which are associated with gastric tumor development." (PMID 27323780, 2016). "We speculate that similar mechanisms may also be important during the development of gastrin-related gastric tumors in vivo." (PMID 27323780, 2016). "We hypothesised that gastrin may exert some of its pro-tumorigenic effects in the stomach by altering the expression of specific microRNAs, which in turn alter the expression of downstream proteins regulating key cellular processes involved in gastric tumor progression." (PMID 27323780, 2016). "The gastric tumour cell line, MKN45, is gastrin-responsive and would be an ideal model for screening potent receptor antagonists." (PMID 2713241, 1989).
duodenal ulcer (14 papers, 2011 to 2026). An ulcer in the duodenal wall. "This disruption interrupts the normal feedback inhibition of gastrin release by luminal acid, leading to elevated gastrin levels and increased acid secretion, as seen in patients with H. pylori-associated duodenal ulcers." (PMID 39569223, 2024). "A mainly antral infection is associated with hypersecretion of gastrin, subsequent increased acid secretion and duodenal ulcer disease, whereas infection in the fundic mucosa reduces gastric acid production and associates with adenocarcinoma development." (PMID 34209478, 2021). "We further analyzed Smad 7, NFkB, IL1B and gastrin expression in antral gut biopsy samples of patients with H. pylori associated duodenal ulcer and normal individuals." (PMID 21445336, 2011). "The fall in maximal (penta)gastrin stimulated acid secretion seen after Hp eradication in patients with duodenal ulcer probably reflects a fall in ECL cell density since maximal gastrin stimulated acid secretion is dependent on the ECL cell mass." (PMID 31108898, 2019). "When she first presented with a duodenal ulcer at 2 years of age, her serum gastrin levels had ranged between 700 and 1000 pg/ml." (PMID 27464496, 2016). "In patients with duodenal ulcers, gastrin tends to be elevated in the bloodstream and there is an increased gastrin response to feeding, and an impairment of the ability of low pH to inhibit gastrin." (PMID 25698559, 2015). "Duodenal ulcer is characterized by increased basal and stimulated acid secretion which results due to perturbation of its major modulators, the gastrin-somatostatin hormone axis." (PMID 21445336, 2011). "In contrast, an indirect mechanism might be that shift workers have increased levels of secretion of serum gastrin (G) and group 1 pepsinogen (PG1) and it has been speculated that such increases may mediate the elevated risk for both gastric and duodenal ulcers in shift workers." (PMID 32130268, 2020). "Regarding the relationship between gastroduodenal ulcers and PCC, studies have shown that some PCC patients have elevated serum adrenaline and gastrin levels both basally and in response to food intake." (PMID 41598318, 2026). "In duodenal ulcer disease, the acid secretion is increased due to Hp infection in the antrum leading to NH3 production and stimulation of gastrin release." (PMID 31108898, 2019). "We observed that individuals with duodenal ulcer had significantly lower levels of IL1B, Smad 7, NFkB and corresponding higher level of gastrin expression." (PMID 21445336, 2011). "We presumed that the antral mucosa inside the duplication in our case had no hydrogen ion feedback inhibition of gastrin release from gastrin cells and increased release of gastrin from the mucosa inside the duplication led to the duodenal ulcer." (PMID 27464496, 2016).
Atrophy (13 papers, 2011 to 2023). Any weakening or degeneration, especially through lack of use. "Preferably, oxyntic atrophy should be assessed by gastrin elevation, which also would allow the evaluation of the role of gastrin versus H. pylori in combination with the genetic variations." (PMID 37686307, 2023). "Gastrin-17 alone resulted in lower specificity (67.5% and 67.7%) and sensitivity (6.3% and 6.8%) than pepsinogen testing to detect severe atrophy or severe IM, respectively." (PMID 35885649, 2022). "High serum gastrin and low pepsinogen-I and I/II ratio are predictors even in the case of severe atrophy, suggesting their usefulness when the diagnosis of AIG is difficult or as serological screening tests." (PMID 35273265, 2022). "The cutoff values of serum gastrin levels (≥ 355 pg/mL) and low PG I/II ratio (≤ 1.8) can be used in both the general population and those with endoscopic atrophy (≥ O3)." (PMID 35273265, 2022). "We counted the number of positive items among the 4 tests: elevated serum gastrin, endoscopic O-p atrophy, 3 + PG test and low serum vitamin B12." (PMID 35410175, 2022). "Subsequent gastrin-induced hyperplasia of ECL cells due to gastric atrophy supports the emergence of Type 1 gastric carcinoids that constitute a majority of gastrin-dependent tumors." (PMID 35330921, 2022). "Further study is needed to evaluate the relationships between hepcidin and gastric mucosal atrophy using the gastrin and/or pepsinogen I/II ratio." (PMID 23533385, 2013). "On the contrary, the rise of gastrin and the presence of IFA, in association with PCA, are highly predictive for AIG and atrophy, as apparent from the data obtained in the first two groups of patients." (PMID 23251219, 2012). "We could not find significant differences between florid and end stages in serum gastrin, PGs, vitamin B12 or endoscopic atrophy in the present study." (PMID 35410175, 2022). "The affections interfere stomach functions by causing particularly failures in secretion of hydrochloric acid and intrinsic factor from oxyntic glands in corpus atrophy, and failures in synthesis and secretion of gastrin-17 from antral G cells in antral atrophy." (PMID 25901896, 2015). "In our study, gastrin (355 pg/mL) and PG I/II ratio (1.8) exhibited the same cutoff values for the prediction of AIG in both the overall study cohort and the subset of patients with advanced atrophy." (PMID 35273265, 2022). "This suggests that PPI use has a larger impact on gastrin production than that induced by active H. pylori infection in the absence of gastric mucosal atrophy." (PMID 34867785, 2021). "Gastrin and pepsinogen levels are not specific for diagnosis of AIG but predict the level of atrophy." (PMID 27671008, 2016).
Hypercalcemia (13 papers, 2008 to 2025). An abnormally increased calcium concentration in the blood. "As has been already discussed at the diagnostic section, the hypercalcaemia of hyperparathyroidism increases gastrin secretion and, by a mechanism unknown, reduces the sensitivity of acid secretion to anti-secretory medication." (PMID 24213225, 2012). "Only after repeated admissions, elevated fasting gastrin levels, and biochemical evidence of hypercalcemia with raised parathyroid hormone (PTH) was MEN1 suspected and subsequently confirmed on genetic testing." (PMID 41541958, 2025). "Biochemical investigations demonstrated persistent hypercalcemia, elevated parathyroid hormone, and significantly raised fasting gastrin levels whilst off high-dose PPI, raising suspicion for MEN1 syndrome." (PMID 41541958, 2025). "Some studies show increased gastrin secretion in hypercalcemia, potentially leading to ulcers and GI bleeding." (PMID 40134958, 2025). "Ca is involved in the secretion of gastrin by the stomach G cells, leading to increased gastrin serum levels in patients with hypercalcemia." (PMID 36496782, 2022). "As mentioned, gastrin is released in response to hypercalcemia (an elevated calcium level in the blood), suggesting that p38 can regulate gastrin through calcium." (PMID 30791472, 2019). "Gastrin is produced in the G cells of the duodenum and in the pyloric antrum of the stomach, and is released in response to certain stimuli such as hypercalcemia (elevated levels of calcium in the blood)." (PMID 30791472, 2019). "Hypercalcaemia is associated with increased acid discharge, since the secretion of gastrin and calcitonin is stimulated by the hypercalcaemia via the intermediary of the CaSR present in the gastrin-secreting cells." (PMID 28122587, 2017). "An earlier publication demonstrated that, in subjects with primary hyperparathyroidism, PTH does not affect gastrin levels and that chronic moderate hypercalcemia does not raise serum fasting gastrin, at least in clinical conditions." (PMID 33510787, 2021). "Lastly, a possible effect of undiagnosed mild hypercalcemia on serum gastrin concentrations cannot be entirely excluded as blood free (ionized) calcium was not measured in the dogs in this study." (PMID 29115998, 2017). "Instead, Zaniewski and colleagues demonstrated that chronic hypercalcemia of either parathyroid or nonparathyroid origin may elevate serum gastrin concentrations." (PMID 33510787, 2021).
insulinoma (13 papers, 2012 to 2024). "It is worth noting that other peptides, including gastrin and insulinoma, can also be elevated in patients with VIPomas." (PMID 37623030, 2023). "Moreover, the index case initially presented with an insulinoma at 24, experienced a relapse at 25, and exhibited metastatic spread to two lymph nodes, with one testing positive for gastrin and ACTH." (PMID 39104820, 2024).